CTLA4 (cytotoxic T-lymphocyte associated protein 4)
Diseases named in the same sentence as CTLA4 in open-access papers (continued):
Sharing a sentence is not in itself a finding about the gene and the disease.
melanoma (continued). "A retrospective review of patients with advanced melanoma and pre-existing autoimmune disorders has only been conducted for patients who received ipilimumab (anti-CTLA-4) and results showed generally exacerbations of their autoimmune symptoms that were manageable." (PMID 27777773, 2016). "A better understanding of additional inhibitory molecules and pathways beyond PD-1/PD-L1 and CTLA-4 regulating melanoma initiation and progression that could be used as therapeutic targets or biomarkers is needed." (PMID 27248166, 2016). "Anti-CTLA-4 (cytotoxic T-lymphocyte-associated protein 4) and anti-PD-1 (programmed cell death protein 1) monoclonal antibodies were approved by the U.S. FDA for the treatment of melanoma and are undergoing clinical trials for the treatment of many other tumors." (PMID 28036020, 2016). "Importantly, anti-PD-1 was superior to anti-CTLA-4 in the treatment of advanced melanoma in terms of progression-free survival (PFS; 47.3 versus 26.5%)." (PMID 27847783, 2016). "Moreover, in melanoma patients who responded to anti-CTLA-4 treatment, the abundance in the stool of Bacteroides thetaiotaomicron and B. fragilis correlated with the response to therapy." (PMID 28018236, 2016). "The abscopal effect; or the phenomenon in which tumor regression occurs at sites distant from the site of radiation, has been documented in melanoma and NSCLC patients who underwent radiation with ipilimumab, a CTLA-4 (cytotoxic T-lymphocyte-associated protein 4) checkpoint inhibitors." (PMID 27895920, 2016). "However, efficacy of anti-CTLA4 and anti-PD1 as single agents has been greatest in malignancies that harbor a high rate of mutation, such as melanoma and some lung carcinoma, suggesting that TSA-directed immune responses are prevalent." (PMID 28003994, 2016). "In addition, 1MT (indoximod) plus anti-CTLA-4 (ipilimumab) or anti-PD-1 is being tested in melanoma patients (NCT02073123) in a phase I/II study." (PMID 27847783, 2016). "Callahan and colleagues review the efficacy and toxicity of this potent combination of checkpoint blockade antibodies in trials of melanoma, renal cell carcinoma, and non-small cell lung cancer in their article “CTLA-4 and PD-1 pathway blockade: combinations in the clinic”." (PMID 26442210, 2015). "Recognition of the immunogenic nature of melanoma has resulted in the development of several immunotherapeutic agents for its treatment, including ipilimumab and pembrolizumab, antibodies respectively blocking CTLA-4 and PD-1." (PMID 26305550, 2015). "Human antibodies directed against immune checkpoint proteins: cytotoxic T lymphocytes antigen-4 (CTLA-4) and programmed death-1 (PD-1), programmed death-ligand 1 (PD-L1), have shown therapeutic efficacy in advanced melanoma and non-small-cell lung cancer and other malignancies." (PMID 26060497, 2015). "Indeed, various pre-clinical and clinical studies have already proven the efficiency of anti-CTLA-4 therapy, especially for melanoma in multimodal settings." (PMID 26500646, 2015). "While blockade of the cytotoxic T-lymphocyte antigen-4 (CTLA-4) T cell regulatory receptor has become a commonly utilized strategy in the management of advanced melanoma, many questions remain regarding the use of this agent in patient populations with autoimmune disease." (PMID 25992290, 2015). "Moreover, IDO inhibitors enhance the therapeutic efficacy of anti-CTLA-4 treatment leading to intratumoral accumulation of T cells and improved survival in the B16 melanoma model." (PMID 26500653, 2015). "In particular, targeting of the inhibitory receptors CTLA-4 and PD-1 or its ligand PD-L1 have been shown to be beneficial for patients with melanoma, renal cell cancer, non-small cell lung cancer and a growing list of other cancers with impressive response rates." (PMID 25901283, 2015).
melanoma (continued). "In this report, we sought to test the hypothesis that combination of high-dose IL-2 and CTLA-4 blockade could mediate more profound therapeutic activity using the B16 melanoma tumor model." (PMID 25992289, 2015). "Importantly, immunomodulating agents have demonstrated significant clinical benefit in melanoma and include immune checkpoint blockade agents such as anti-CTLA4 and anti-PD1/PDL1." (PMID 26545983, 2015). "As with anti-CTLA-4, the anti-PD-1/PD-L1 story starts with melanoma." (PMID 26137543, 2015). "Although new immune based approaches such as anticytotoxic T lymphocyte antigen 4 (anti-CTLA-4) and antiprogrammed death 1 (anti-PD-1) have shown considerable promise in a subset of melanoma patients, systemic chemotherapy is still considered an option for advanced melanoma." (PMID 25922565, 2015). "Just recently, the combination of anti-CTLA-4 and anti-PD-1 was reported to significantly increase the fraction of melanoma patients responding to immunotherapy compared to anti-CTLA-4 monotherapy-treated patients, emphasizing the different modes of action of CTLA-4 and PD-1." (PMID 26500653, 2015). "Clinically, combining anti-CTLA4 (ipilimumab) with anti-PD-1 (nivolumab) antibodies resulted in even greater anti-tumor efficacy, as tumor regression occurred in 80% of patients with advanced melanoma." (PMID 25614821, 2015). "Importantly, a recent phase I trial demonstrated that the combination of PD-1 and CTLA-4 blockade produces greater than additive response rates in melanoma patients, with an ORR of 42%." (PMID 25941561, 2015). "After separate testing of results from NPS analysis of melanoma case CTLA-4 genotype relationship profiles, we found the simplest and statistically most significant results were obtained when the RRP1−RRP20 resulting from the analysis of combined case/control cohort were used." (PMID 24475110, 2014). "Following the encouraging data from the Ipilimumab clinical study in malignant melanoma, the suppression of CTLA4 expression on lymphocytes could be a new strategy in the therapy of some immunogenic cancers." (PMID 24608924, 2014). "While the combination of anti-4-1BB and anti-CTLA-4 antibodies produced tumor rejection in these two commonly less aggressive tumor types, the same therapy failed to produce tumor growth delay in the highly aggressive B16 melanoma model." (PMID 25013914, 2014). "Importantly, using pre-clinical animal melanoma models it was recently shown that IDO is responsible for mediating resistance to anti-CTLA-4 and anti-PD-1 therapy." (PMID 24782858, 2014). "Similarly, anti-CTLA-4 agents approved for treatment of melanoma have been tested in advanced stage SCLC and NSCLC, though results for SCLC are thus far inconclusive." (PMID 25523825, 2014). "Selected clinical trials of CTLA-4 and PD-1 pathway blocking antibodies in advanced melanoma." (PMID 25642417, 2014). "In alignment with this line of thinking, the combination of anti-CTLA-4 and anti-PD-1 antibody treatment in a mouse B16 melanoma study led to substantial reduction in Treg cells as well as myeloid cells with a concomitant increase in tumor-infiltrating effector T cells." (PMID 23874336, 2013). "The degree of ADCC is dependent on the expression level of CTLA-4 on melanoma target cells." (PMID 23634660, 2013). "The heterogeneity of level of CTLA-4 expression on melanoma cell lines may derive from the heterogeneity of the parental tumor tissue from which the cell line has been obtained." (PMID 23634660, 2013). "Herein, we show that patient derived melanoma cell lines and tumor tissues can express CTLA-4." (PMID 23634660, 2013). "Indeed, we suggest that the activation of ADCC leading to melanoma cell lysis can concur with the triggering of immune response due to relieve of CTLA-4-mediated down-regulation to a better elimination of melanoma cells." (PMID 23634660, 2013).
melanoma (continued). "That NK cells may be involved in the elimination of CTLA-4+ melanoma cells it has been confirmed in a chimeric murine xenograft model as well." (PMID 23634660, 2013). "We next investigated whether CTLA-4 expressed by melanoma cells was recognized by the therapeutic Ipilimumab antibody." (PMID 23634660, 2013). "A recent hallmark immunotherapeutic study using a dual mAb treatment approach to block the immune checkpoint regulators CTLA-4 and programed death-1 (PD-1) using Ipilimumab and Nivolumab, respectively, resulted in persistent tumor regression in advanced melanoma patients." (PMID 24427158, 2013). "The expression in vivo of CTLA-4 on melanoma cells would suggest that ADCC could be triggered also upon in vivo administration of Ipilimumab." (PMID 23634660, 2013). "In other models, anti-CTLA4 antibody treatment has been reported to enhance the T-cell mediated tumour rejection of colon carcinoma, melanoma, prostate cancer in mouse models as well as in human cancer patients, although treatment induced autoimmunity can occur." (PMID 23799135, 2013). "We further investigated whether Ipilimumab could trigger activation of NK cells to ADCC upon interaction with CTLA-4+ melanoma cells." (PMID 23634660, 2013). "Furthermore, we show that ADCC and TNF-α secretion are triggered in FcγRIIIA+ lymphocyte subsets upon Ipilimumab interaction with CTLA-4 on melanoma cells." (PMID 23634660, 2013). "Furthermore, NK cells in the presence of Ipilimumab interacting with CTLA-4+ melanoma cells can release TNF-α." (PMID 23634660, 2013). "Accordingly, about 2/3 of melanoma specimens expressed CTLA-4 at different level of intensity." (PMID 23634660, 2013). "Furthermore, the efficacy of CTLA-4 blockade as a single treatment seems to be limited to intrinsically immunogenic tumors such as melanoma." (PMID 24348481, 2013). "This further reinforces the idea that in vivo melanoma cells can express CTLA-4." (PMID 23634660, 2013). "Despite substantial recent advancements in melanoma therapy with T-cell antibodies such as anti-CTLA4 and anti-PD1, or with targeted therapies such as BRAF or MEK inhibitors, adoptive cell therapy with tumor infiltrating lymphocytes still offers the most robust clinical cure rates." (PMID 23483943, 2013). "TNF-α was released upon interaction of NK cells with CTLA-4+ melanoma cell lines." (PMID 23634660, 2013). "Two human anti-CTLA-4 IgG mAbs, Ipilimumab (Bristol-Myers Squibb, Princeton, NJ) and Tremelimumab (Pfizer, New York, NY), have been used, either alone or in combination with vaccines, in the immunotherapy of melanoma." (PMID 23634660, 2013). "We next analyzed whether Ipilimumab could also trigger ex-vivo NK cells to produce anti-tumor cytokines, such as TNF-α, during co-cultures with CTLA-4+ melanoma cells." (PMID 23634660, 2013). "However, preclinical studies showed that blocking of CTLA-4 results in anti-tumor activity and tumor regression in many mice tumor models (prostate, breast, lymphoma, melanoma), which paved the way for clinical studies." (PMID 22778766, 2012). "We reviewed the result of randomized phase II-III clinical studies testing anti-CTLA-4 antibodies (ipilimumab and tremelimumab) for the treatment of melanoma to focus on practical or scientific questions related to the broad utilization of these products in the clinics." (PMID 22077981, 2011). "However, evidence of tumor regression with prolonged time to progression has been seen in patients with melanoma who received cytotoxic T lymphocyte antibodies (CTLA-4)." (PMID 22093436, 2011). "We hypothesized that increasing the tumor-specific T-cell frequency through vaccination would allow us to better observe the interaction between 4-1BB activation and CTLA-4 blockade in the B16 melanoma system." (PMID 21559358, 2011). "In an OVA-expressing melanoma model, CTLA-4 blockade and depletion of regulatory T cells could further enhance cryoinduced tumor-specific T-cell responses." (PMID 22242035, 2011).
melanoma (continued). "Finally, higher proportions of tumor-reactive T cells co-expressing CCL4, IFN-γ, and TNF-α were detected in melanoma patients with favorable clinical responses to α-CTLA-4 treatment." (PMID 21203522, 2010). "There were no statistical differences in the incidence of CTLA-4 polymorphisms between melanoma patients and healthy controls, except for JO 31, where the T/T allele was higher in controls (33.3% vs 24.3%) while G/G and G/T was lower (p = 0.047)." (PMID 21044351, 2010). "In fact, understanding how melanoma overcomes host immunity could be the key to developing strategies targeting components of the antitumor immune response, for example, anti-CTLA-4 agents, which has produced encouraging results." (PMID 20936106, 2010). "No database was available that describes the prevalence of CTLA-4 alleles among the Greek population, nor of melanoma patients from Greece." (PMID 21044351, 2010). "However, even with this analysis, we were unable to correlate the activation or expansion of circulating melanoma antigen-specific CD8+ T cells with clinical benefit to CTLA4 blockade." (PMID 18452610, 2008). "CTLA4-blocking antibodies induce tumor regression in a subset of patients with melanoma." (PMID 18452610, 2008). "Moreover, it is also demonstrated that both mechanisms, Tregdepletion and CTLA-4 blockade, can work synergistically on enhancing antitumor immunity in experimental B16 melanoma." (PMID 18317534, 2007). "Also, in several in vivomodels for disease disorders, it was demonstrated that CTLA-4 blockadeabrogates the suppressive function of murine (e.g., inflammatory bowel disease) and human (e.g., melanoma patients) Tregs." (PMID 18317534, 2007). "As a hypothesis-generating human anchor, in melanoma patients treated with anti-CTLA-4, AR and B7-H3 show no pre-treatment association, but a positive association emerges post-treatment." (PMID 41958557, 2026). "Additionally, ITGA4 expression varied among multiple Immunosuppressive datasets, showing high levels in METABRIC, TCGA Melanoma, ICB_Nathanson2017_CTLA4, and ICB_VanAllen2015_CTLA4 cohorts, but low in GSE12417_GPL570, Patel2017 1, and Shifrut 2018 pilot Average cohorts." (PMID 40012546, 2025). "Compared to Vδ2 T cells engineered with the isotype control (IgG) antibody, anti CTLA-4/anti PD-1 Vδ2 T cells showed a marked increase in melanoma spheroid infiltration and reduction of spheroid volume, indicating an improved killing efficacy of melanoma cells." (PMID 40148988, 2025). "Similarly, TIDE simplifies immune evasion into a few gene markers (e.g., PD–1, CTLA–4), and its model is mainly trained on melanoma and non-small-cell lung cancer (NSCLC) data, potentially limiting its applicability to CRC due to distinct tumor biology and immune contexts." (PMID 40864806, 2025). "The real breakthrough in melanoma patients’ treatment with metastasis was the biological activity of monoclonal antibodies working as immunomodulators, like ipilimumab or nivolumab, blocking the repressor of T lymphocyte activation (CTLA-4) and programmed cell death protein (PD-1)." (PMID 40564101, 2025). "Additionally, an analysis of seven SNPs (rs733618, rs4553808, rs11571317, rs5742909, rs231775, rs3087243, and rs7565213) in melanoma patients treated with CTLA-4 blockade revealed that specific SNPs, such as rs4553808, rs11571327, and rs231775, were linked to treatment response." (PMID 41244914, 2025). "In addition to targeted therapies (TT), the use of immune checkpoint blockade (ICB) against programmed cell death‐1 (PD‐1) protein or cytotoxic T lymphocyte antigen‐4 (CTLA‐4) has also greatly improved the treatment of advanced melanoma, with notable efficacy and long‐term survival benefits." (PMID 39968494, 2025).
melanoma (continued). "We investigated whether DBCO–anti–4-1BB with MazNP (TRACER) enhances the efficacy of immunotherapy in the poorly immunogenic B16F10 melanoma syngeneic tumor model, which responds poorly to checkpoint therapies such as single-agent treatment or combinations of anti–4-1BB and anti–CTLA-4 antibodies." (PMID 40067370, 2025). "The treatment landscape for advanced melanoma has transformed significantly with the advent of BRAF and MEK inhibitors (BRAF/MEKi) targeting BRAFV600 mutations, as well as immune checkpoint inhibitors (ICI) like anti-PD-1 monotherapy or its combinations with anti-CTLA-4 or anti-LAG-3." (PMID 39859576, 2025). "Anti-PD-1 antibodies have been at the forefront of this success but the first of the ICI to be introduced, anti-CTLA-4 antibodies, have faced difficulties preventing broad therapeutic application, despite evidence of an enduring anti-tumour immunity in some cancers, notably melanoma." (PMID 40265076, 2025). "Evaluation of melanoma data from The Cancer Genome Atlas (TCGA) revealed strong positive correlations between PDPN expression and several immune checkpoint receptors, including PD-L1, CTLA4, LAG3, TIGIT, and BTLA, with the association with PD-L1 (CD274) being the most prominent (r=0.504, p<0.001)." (PMID 41573582, 2025). "In immunotherapy, particularly immune checkpoint inhibitors (ICIs) such as anti-PD-1/PD-L1 and anti-CTLA-4 therapies, studies have shown that maintaining VD levels within the normal range during anti-PD-1 immunotherapy is necessary to ensure treatment efficacy in patients with advanced melanoma." (PMID 40806182, 2025). "Immune checkpoint inhibitors (ICI) that target cytotoxic T-lymphocyte-associated protein 4 (CTLA-4) and programmed cell death protein 1 (PD-1) and its ligand (PD-L1) have significantly transformed the treatment of a variety of cancers, such as melanoma, lung and genitourinary cancers." (PMID 38833685, 2024). "Furthermore, in another study analyzing flow cytometry data with supervised clustering from PBMCs in 90 advanced melanoma patients treated with anti-PD-1 and anti-CTLA-4 combinations, an increase in circulating CD4+ Tem cells correlated positively with longer PFS." (PMID 39273452, 2024). "Therefore, whether anti-CTLA4 is the best option to combine with anti-PD1/L1 for the treatment of melanoma and other malignancies is a critical question that remains to be answered." (PMID 38539487, 2024). "Phase I clinical trials have proven the safety and efficacy of pembrolizumab in treating melanoma, and phase II clinical trials have shown that pembrolizumab’s efficacy in treating advanced melanoma is significantly superior to that of ipilimumab (anti-CTLA-4 antibody)." (PMID 38762484, 2024). "Single or combination immune checkpoint inhibitors, such as anti-cytotoxic T-lymphocyte associated protein 4 (CTLA-4) and anti-programmed cell death 1 (PD-1), associated with stereotactic RT showed remarkable and durable responses in patients with BM from melanoma without severe side effects." (PMID 38893165, 2024). "However, combined blockade with anti-PD-1 and anti-CTLA-4 may potentiate Th1 cells, which are characterized by their production of IFN-γ and have been associated with a better prognosis in melanoma patients." (PMID 39273452, 2024). "Furthermore, while combination anti–PD-1 and anti–CTLA-4 blockade was ineffective against weakly immunogenic melanoma tumors in mice, adding DNA-PKi (NU7441) in conjunction with STGL and anti-CD40 (NU-SL40) or knocking out DNA-PK in tumors resulted in tumor regression in 75%–100% in mice." (PMID 39436696, 2024). "Indeed, a report showed that melanoma with positive NY-ESO-1 immune response responded to anti–CTLA-4 therapy, and other reports showed that lung adenocarcinoma with serum NY-ESO-1 antibody responses had a better clinical efficacy to anti-PD-1 therapy than those without antibody responses." (PMID 38326601, 2024).